ANKRD26P1 (ankyrin repeat domain 26 pseudogene 1)
Synonyms: FLJ43980
Gene: Transcribed unprocessed pseudogene on chromosome 16 (46,518,305 to 46,568,915, reverse strand). Ensembl gene ENSG00000261239.
Diseases named in the same sentence as ANKRD26P1 in open-access papers:
ANKRD26P1 is named in the same sentence as 1 disease in open-access papers, as found by Europe PMC text mining. Sharing a sentence is not in itself a finding about the gene and the disease.
ANKRD26P1 shares sentences with these, for which no sentence is quoted: viral infection (1 paper).